RALB (RAS like proto-oncogene B)
Description:
Multifunctional GTPase involved in a variety of cellular processes including gene expression, cell migration, cell proliferation, oncogenic transformation and membrane trafficking. Accomplishes its multiple functions by interacting with distinct downstream effectors. Acts as a GTP sensor for GTP-dependent exocytosis of dense core vesicles (By similarity). Required both to stabilize the assembly of the exocyst complex and to localize functional exocyst complexes to the leading edge of migrating cells (By similarity). Required for suppression of apoptosis. In late stages of cytokinesis, upon completion of the bridge formation between dividing cells, mediates exocyst recruitment to the midbody to drive abscission. Involved in ligand-dependent receptor mediated endocytosis of the EGF and insulin receptors.
Tractability: Small molecule: a structure with a bound ligand is known; it has a high-quality binding pocket. Antibody: UniProt places it where antibodies can reach, with high confidence; its Gene Ontology location is reachable by antibodies, with high confidence. PROTAC: ubiquitination databases record sites on it; its protein half-life has been measured.
Target class: Enzyme; Hydrolase
Gene: Protein-coding gene on chromosome 2 (120,240,050 to 120,305,300, forward strand). Ensembl gene ENSG00000144118.
Subcellular location: Cell membrane; Midbody
Pathways (Reactome):
Signal Transduction: p38MAPK events
Gene Ontology:
Molecular function: ATPase binding; GDP binding; GTP binding; GTPase activity; protein binding; ubiquitin protein ligase binding; G protein activity
Biological process: positive regulation of autophagosome assembly; positive regulation of epidermal growth factor receptor signaling pathway; positive regulation of innate immune response; receptor internalization; Ras protein signal transduction; regulation of exocyst assembly; regulation of exocyst localization; signal transduction
Cellular component: extracellular exosome; midbody; plasma membrane; membrane
Genetic constraint (gnomAD): Loss-of-function variants: 16 observed, 20.64 expected, observed/expected ratio (o/e) 0.78, 90% interval 0.52 to 1.18. The upper end of that interval is the gene's LOEUF score, 1.18, which puts it in group 5 of 6, group 1 being the genes least tolerant of losing a copy. Missense variants: 140 observed, 234.95 expected, observed/expected ratio (o/e) 0.6, 90% interval 0.52 to 0.69. Synonymous variants: 85 observed, 90.43 expected, observed/expected ratio (o/e) 0.94, 90% interval 0.79 to 1.13.
Homologues: Orthologues: chimpanzee RALB (100% identical), guinea pig RALB (99% identical), macaque RALB (99% identical), pig RALB (99% identical), dog RALB (98% identical), rabbit RALB (98% identical), mouse Ralb (95% identical), zebrafish ralba (94% identical), tropical clawed frog ralb (94% identical), rat Ralb (83% identical), zebrafish ralbb (41% identical). Paralogues in human: RALA (82% identical), RRAS2 (47% identical), KRAS (46% identical), HRAS (45% identical), RRAS (45% identical), NRAS (44% identical), RAP1A (44% identical), RAP1B (43% identical), RIT1 (42% identical), MRAS (41% identical), RIT2 (40% identical), RAP2A (38% identical), and 23 more.
Diseases named in the same sentence as RALB in open-access papers:
RALB is named in the same sentence as 48 diseases in open-access papers, as found by Europe PMC text mining. Sharing a sentence is not in itself a finding about the gene and the disease. The quoted sentences say what the papers report.
breast carcinoma (10 papers, 2018 to 2025). "It has also been reported that elevated expression of both RALA and RALB are associated with poor outcome in the TCGA breast cancer patient cohort." (PMID 34118960, 2021). "To evaluate the general prognostic importance of RALA and RALB in BC subtypes associated with RAS activation, we generated Kaplan–Meier survival plots using data from the KM Plotter breast cancer metacohort." (PMID 39272901, 2024). "Emerging evidence also suggests that RALB is involved in breast cancer progression through similar mechanisms, including cell migration and immune evasion, highlighting its broader role in mammary tissue biology." (PMID 41239602, 2025). "Recent work by Vincent Hyenne’s group has found a critical role for RALA and RALB in extracellular vesicle trafficking, driving breast cancer metastasis." (PMID 35626682, 2022). "Another recent study found a correlation between RALB protein expression and progression toward metastasis in human breast cancer samples." (PMID 35626682, 2022). "For example, RALA is required for invasion of MDA-MB-231 breast cancer cells, but in bladder cancer RALB is found to support invasion." (PMID 35626682, 2022). "In silico analyses utilizing the large TCGA and METABRIC breast cancer patient gene expression databases uncovered paradoxical associations between survival and RALA and RALB expression in support of our in vitro and in vivo findings." (PMID 34118960, 2021). "We next used gene expression data from the Broad Institute Cancer Cell Line Encyclopedia (CCLE) to examine RALA and RALB expression across a panel of 46 breast cancer cell lines." (PMID 34118960, 2021). "The prognostic significance of RALA and RALB expression was next analyzed across all breast cancer subtypes in the METABRIC and TCGA datasets." (PMID 34118960, 2021). "In the TCGA, RALA expression is significantly increased in TNBC relative to normal mammary tissue or other breast cancer subtypes while RALB expression is significantly decreased in TNBC relative to normal mammary tissue or other breast cancer subtypes." (PMID 34118960, 2021). "RALB, also known as RAS Like Proto-Oncogene B, is known for its role in invasion and metastasis across cancers and specifically for breast cancer." (PMID 33892787, 2021). "Using a large cohort of breast cancer patients with metastatic progression from the Cancer Genome Atlas (TCGA), we found that high expression of either RalA or RalB is significantly correlated with reduced survival." (PMID 33404012, 2021). "We have previously shown that RalA and RalB control EV secretion in aggressive 4T1 mammary tumor cells that reliably mimics the aggressive phenotype of human triple-negative breast cancer." (PMID 33404012, 2021). "We measured the number and the surface covered by metastatic foci in serial lung sections and observed that RalA or RalB depletion in mammary tumors drastically reduced their metastatic potency." (PMID 33404012, 2021). "This group has also shown that shRNA knockdown of either RALA or RALB in 4T1 mammary tumor cells leads to a significant reduction in secreted exosome-like vesicles and reduced lung metastatic capacity." (PMID 34118960, 2021). "It has previously been reported that RALA and RALB regulate pro-metastatic extracellular vesicle secretion in the 4T1 mouse mammary tumor model, and contradictory effects of RALB silencing, with RALB loss decreasing tumor volume in vivo but increasing proliferation in vitro, were also observed." (PMID 39272901, 2024). "In the METABRIC cohort, RALA expression is not significantly different between TNBC and other BC subtypes but is increased in BC relative to normal mammary tissue while RALB expression is significantly decreased in TNBC relative to normal mammary tissue or other breast cancer subtypes." (PMID 34118960, 2021). "In fact, RALB was recently reported to be necessary for invasion in breast cancer." (PMID 34118960, 2021).
breast carcinoma (continued). "Having identified RalA and RalB as important regulators of EV secretion in breast cancer cells, we next investigated whether such a function could impact metastasis." (PMID 33404012, 2021). "Finally, we identify the adhesion protein CD146/MCAM as a key EV cargo controlled by RalA and RalB and demonstrate that it conveys, in part, the pro-metastatic function to EVs by controlling the lung tropism of breast cancer EVs." (PMID 33404012, 2021). "In addition, RalB expression at the protein level in breast cancer increased in a manner consistent with progression toward metastasis." (PMID 33917100, 2021). "Finally, we show that high levels of RalA and RalB correlated with poor prognosis suggesting a unified mechanism for human breast cancer metastasis." (PMID 33404012, 2021). "Finally, we analyzed Ral proteins’ expression in a cohort of breast cancer samples, pointing out for the first time a potential role of RalB in the invasiveness and metastatic spread of human breast cancers." (PMID 30320548, 2018). "In this work we examined Ral protein expression in patient breast tumor samples and we found overexpression of both RalA and RalB as compared to normal breast tissues, therefore adding breast cancers to the list of human cancers with potential overstimulation of Ral pathway." (PMID 30320548, 2018). "Moreover, on the clinical side, we uncovered a potential role of RalB in human breast cancers by determining that RalB expression at protein level increases in a manner consistent with progression toward metastasis." (PMID 30320548, 2018). "(C) Representative RalB immunostaining in the different breast cancer compartments." (PMID 30320548, 2018). "In contrast, RALB was associated with an increased risk of ER-negative [OR: 1.40, 95% CI: 1.20 to 1.64; PP4: 0.93] and HER2 enriched tumours [OR: 1.59, 95% CI: 1.14 to 2.25; PP4: 0.98], as well as breast cancer overall [OR: 1.16, 95% CI: 1.09 to 1.23; PP4: 0.70]." (PMID 38684708, 2024). "(D) Invasion of human breast cancer cells requires RalB, regardless of Ras mutational status." (PMID 30320548, 2018). "Next, we analyzed RALA and RALB mRNA expression in the large TCGA and METABRIC breast cancer patient datasets." (PMID 34118960, 2021). "We further demonstrate that RalA and RalB promote lung metastasis without affecting the invasive potential of breast carcinoma." (PMID 33404012, 2021). "In this larger panel it, was clear that, while RALA expression does not vary across BC cell lines, RALB expression is significantly reduced in luminal and TN breast cancer cell lines relative to HER2+ lines." (PMID 34118960, 2021). "Finally, RalA, RalB, and MCAM/CD146, are factors of poor prognosis in breast cancer patients." (PMID 33404012, 2021). "With the limitation that RalB amount does not necessarily reflect RalB activity, these results suggest that RalB might have a role in human breast cancer invasion and metastasis." (PMID 30320548, 2018).
lung carcinoma (9 papers, 2015 to 2024). "Most evidence supports RALA as the more important RAL GTPase in ovarian cancer and prostate cancer, while RALB appears to be more important for cancer progression and metastasis in bladder and lung cancers." (PMID 35626682, 2022). "High RALB expression has been reported in several tumours, including lung cancer, and has been identified as a poor prognostic marker in these tumours." (PMID 33122623, 2020). "Interesting, RALB was required for invasive lung cancer cell behavior through a mechanism dependent on ARHGEF2 activation of the RHOA/ROCK pathway." (PMID 27835861, 2017). "The two highly homologous small GTPases, RAS like Proto-oncogene A (RALA) and B (RALB), activated downstream of RAS, have been implicated in tumor growth and metastasis in a wide variety of cancer types including colorectal cancer, lung cancer, melanoma, and BC." (PMID 39272901, 2024). "In certain cancers, such as pancreatic cancer, melanoma, and lung cancer, both RALA and RALB have been found to promote tumorigenicity." (PMID 39272901, 2024). "BQU57, a derivative of RBC8, disrupted the anchorage-independent growth of human lung cancer cells in vitro and substantially inhibited RALA and RALB activity and tumor growth in vivo." (PMID 39272901, 2024). "Using a KRAS-driven murine lung carcinoma model, other investigators have shown that RALA or RALB activity is required for tumour growth." (PMID 33122623, 2020). "The importance of RALB and TBK1 to RAS-induced lung cancer was confirmed in a RNA inhibitor screen of synthetic lethal partners of oncogenic KRAS, where RALB and TBK1 were identified as top targets." (PMID 31681587, 2019). "Our results explain the role of RAS family and prove that RalB and TKB1 participate in the activation of pro-survival signaling pathway in lung cancer." (PMID 31316001, 2019). "RALA and RALB can have redundant roles, such as in KRAS-driven lung carcinoma." (PMID 35626682, 2022). "Studying the effect of RalB KFA on these phenotypes revealed that RalB KFA enhanced migration of A549 lung cancer cells but did not affect cell proliferation." (PMID 34368168, 2021).
pancreatic cancer (9 papers, 2011 to 2022). "The requirement of RalB for invasion in vitro (by Transwell Invasion assay) was shown by shRNA knock-down approach in seven out of nine K-Ras mutated human pancreatic cancer cell lines." (PMID 30320548, 2018). "RalA and RalB were shown to be activated in pancreatic cancers, aggressive malignancies with high frequency of Ras mutations." (PMID 21714887, 2011). "In other studies, the small noncoding RNA miRNA-139 was found to negatively regulate RALB through a RAL/RAC/PI3K pathway in order to prevent pancreatic cancer in mouse models." (PMID 35626682, 2022). "Additional investigations support the idea that RALB plays a more important role in pancreatic cancer progression than RALA." (PMID 35626682, 2022). "In pancreatic cancer, RALB was activated in cancer tissues, and it enhanced the cells’ invasive ability and their metastatic colonization in in vitro and in vivo studies." (PMID 35409173, 2022). "All these genes are upregulated in pancreatic cancer, and seven of them are significantly associated with unfavorable prognosis (MET, YAP1, PTPN14, EPS8, AHNAK, RALB, and AFAP1)." (PMID 34957301, 2021). "Divergent roles for the RAL proteins have been identified and suggest RALA is critical for tumor initiation whereas RALB is important for tumor metastasis in pancreatic cancer." (PMID 27835861, 2017). "Dinaciclib is an inhibitor of CDK5, an activator of the RALs, shown to reduce pancreatic cancer initiation, progression and metastasis in mouse xenograft models by reducing activation of RALA and RALB." (PMID 35626682, 2022). "Later, it was found that RALA, but not RALB, supports anchorage-independent growth in the pancreatic cancer cell line MiaPaCa2." (PMID 35626682, 2022). "Consistently, another study showed that RalB, but not RalA, plays a role in invadopodia formation in human pancreatic cancer cell lines." (PMID 30320548, 2018). "The roles of Cdk5 in pancreatic cancer formation and progression via Ras-Ral signaling have been further proven by rescue test, in which constitutively activating RalA-GTP and RalB-GTP in pancreatic cancer cells expressing dominant-negative Cdk5 significantly rescued the effects of Cdk5 inhibition." (PMID 28288624, 2017).
bladder cancer (7 papers, 2016 to 2022). "Phosphorylation of S198 at the C‐terminal in RalB by PKC in T24 or UM‐UC‐3 bladder cancer cell lines can cause translocation of RalB from the plasma membrane to the perinuclear region." (PMID 29047224, 2017). "In MEFs and bladder cancer cells, the downregulation of both RalA and RalB activities is required to significantly reduce growth." (PMID 35897776, 2022). "Expression of constitutively active RALA G23V in UMUC-3 bladder cancer cells significantly reduced cell motility whereas RALB G23V stimulated motility significantly." (PMID 35626682, 2022). "Genes up-regulated after knockdown of RALA or RALB [GeneiD=5898;5899], which were also differentially expressed in bladder cancer compared to normal bladder urothelium tissue." (PMID 28423528, 2017). "In bladder cancers RalB is reported to be more active than RalA in some studies, with a reported role in migration, proliferation and anchorage independence as well." (PMID 27269287, 2016). "Phosphorylation of RALB at S198 is required for migration in UMUC3 bladder cancer cells." (PMID 35626682, 2022). "Substantial literature on RAL-GTPases in bladder cancer has been published, supporting divergent roles for RALA and RALB." (PMID 35626682, 2022).
colorectal cancer (4 papers, 2020 to 2025). A primary or metastatic malignant neoplasm that affects the colon or rectum. "(2024) reported that butyrate derived from Roseburia intestinalis enhances the sensitivity of colorectal cancer to RT by activating the OR51E1/RALB axis and promoting autophagy." (PMID 40129929, 2025). "Significantly, high RALB mRNA levels were found in the poor prognostic Colorectal Cancer Intrinsic Subtypes (CRIS)-B CRC subgroup." (PMID 33122623, 2020). "However, in colorectal cancer, the RALs appear to have opposite roles, with stable shRNA knockdown of RALA suppressing and RALB knockdown enhancing anchorage-independent growth in vitro." (PMID 39272901, 2024). "Likewise, in colorectal cancer cell lines, RALA and RALB have antagonistic functions with silencing of RALA decreasing anchorage independent growth while silencing RALB has the opposite effect." (PMID 34118960, 2021).
melanoma (4 papers, 2016 to 2024). A malignant, usually aggressive tumor composed of atypical, neoplastic melanocytes. "Assessment of the levels of active GTP-bound RALA and GTP-bound RALB demonstrated that independently derived melanoma cell lines have much higher GTP-RALA levels and essentially absent GTP-RALB." (PMID 35626682, 2022). "In almost all cancer types examined (pancreas, colon, lung, bladder, prostate, melanoma), increased overexpression and/or activation of both RalA and RalB have been observed in patient tumor samples compared with normal tissues, regardless of their Ras mutation status." (PMID 30320548, 2018). "However RALA and RALB are overexpressed in a number of tumors, most notably NSCLC and melanoma." (PMID 27713118, 2016).
acute myeloid leukemia (3 papers, 2016 to 2022). Acute myeloid leukemia (AML) is a group of neoplasms arising from precursor cells committed to the myeloid cell-line differentiation. "In acute myeloid leukemia (AML), depletion of RALB was shown to phenocopy loss of NRAS(V12), while loss of AKT or MAPK did not." (PMID 35626682, 2022).
non-small cell lung carcinoma (3 papers, 2016 to 2022). A group of at least three distinct histological types of lung cancer, including non-small cell squamous cell carcinoma, adenocarcinoma, and large cell carcinoma. "Dong and colleagues reported that cilengitide reversed erlotinib resistance by inhibiting the Galectin-3/KRAS/RALB/TBK1/NF-κB signaling pathway in non-small cell lung cancer." (PMID 35142593, 2022). "In a mouse model of Kras-driven non-small cell lung carcinoma, expression of either RalA or RalB is sufficient to drive tumor growth." (PMID 31201267, 2019). "Murine knockout studies have shown an essential role for either RALA or RALB in KRAS driven non-small cell lung cancer cell proliferation." (PMID 27556501, 2016).
multiple myeloma (2 papers, 2022). "In the early studies of multiple myeloma (MM), experiments had shown that RALB can promote the migration of OPM-1 and NCI-H929 cells, but RALA did not have this effect." (PMID 36466919, 2022). "RALB has been implicated as the more important RAL paralog for filopodial invasion and migration in normal rat kidney cells, B cells, multiple myeloma, pancreatic UMUC-3 cells and prostate DU145 cells." (PMID 35626682, 2022). "Early work in multiple myeloma (MM) suggests that RALB is important for migration in the OPM-1 and NCI-H929 cell lines." (PMID 35626682, 2022).
pancreatic ductal adenocarcinoma (2 papers, 2021 to 2022). An infiltrating adenocarcinoma that arises from the epithelial cells of the pancreas. "In cancer cells, the RALB-RALBP1 interaction has been shown to promote invadopodia formation in pancreatic ductal carcinoma, with loss of RALB or RALBP1, disrupting the formation of invadopodia." (PMID 35626682, 2022). "RALB has been proven to play an important role in pancreatic ductal adenocarcinoma (PDAC) tumorigenesis and invasive and metastatic growth." (PMID 34957301, 2021).